RN7SL181P (RNA, 7SL, cytoplasmic 181, pseudogene)
Gene: Miscellaneous RNA gene on chromosome 9 (121,203,159 to 121,203,435, forward strand). Ensembl gene ENSG00000243738.
Homologues: Orthologues: chimpanzee Metazoa_SRP (97% identical), macaque Metazoa_SRP (89% identical), dog Metazoa_SRP (60% identical). Paralogues in human: RN7SL2 (80% identical), RN7SL1 (80% identical), RN7SL709P (79% identical), RN7SL3 (79% identical), RN7SL122P (77% identical), RN7SL126P (77% identical), RN7SL597P (77% identical), RN7SL625P (77% identical), RN7SL664P (77% identical), RN7SL43P (77% identical), RN7SL45P (77% identical), RN7SL178P (76% identical), and 700 more.